SEMA4A (semaphorin 4A)
Description:
Cell surface receptor for PLXNB1, PLXNB2, PLXNB3 and PLXND1 that plays an important role in cell-cell signaling (By similarity). Regulates glutamatergic and GABAergic synapse development (By similarity). Promotes the development of inhibitory synapses in a PLXNB1-dependent manner and promotes the development of excitatory synapses in a PLXNB2-dependent manner (By similarity). Plays a role in priming antigen-specific T-cells, promotes differentiation of Th1 T-helper cells, and thereby contributes to adaptive immunity (By similarity). Promotes phosphorylation of TIMD2 (By similarity). Inhibits angiogenesis (By similarity). Promotes axon growth cone collapse (By similarity). Inhibits axonal extension by providing local signals to specify territories inaccessible for growing axons (By similarity).
Synonyms: SEMAB; SEMB; FLJ12287; CORD10; RP35
Tractability: Antibody: UniProt places it where antibodies can reach, with high confidence; its Gene Ontology location is reachable by antibodies, with high confidence; UniProt predicts a signal peptide or a membrane-spanning region. PROTAC: ubiquitination databases record sites on it; its protein half-life has been measured.
Gene: Protein-coding gene on chromosome 1 (156,147,366 to 156,178,869, forward strand). Ensembl gene ENSG00000196189.
Subcellular location: Cell membrane
Pathways (Reactome):
Developmental Biology: Other semaphorin interactions
Gene Ontology:
Molecular function: protein binding; chemorepellent activity; neuropilin binding; semaphorin receptor binding
Biological process: axon guidance; negative chemotaxis; neural crest cell migration; positive regulation of cell migration; positive regulation of excitatory synapse assembly; positive regulation of inhibitory synapse assembly; semaphorin-plexin signaling pathway; axonogenesis; negative regulation of angiogenesis; regulation of cell shape; regulation of endothelial cell migration; T cell differentiation involved in immune response; T-helper 1 cell differentiation
Cellular component: plasma membrane
Genetic constraint (gnomAD): Loss-of-function variants: 53 observed, 77.62 expected, observed/expected ratio (o/e) 0.68, 90% interval 0.55 to 0.86. The upper end of that interval is the gene's LOEUF score, 0.86, which puts it in group 3 of 6, group 1 being the genes least tolerant of losing a copy. Missense variants: 926 observed, 998.15 expected, observed/expected ratio (o/e) 0.93, 90% interval 0.88 to 0.98. Synonymous variants: 369 observed, 414.95 expected, observed/expected ratio (o/e) 0.89, 90% interval 0.82 to 0.97.
Gene-disease validity (ClinGen):
ClinGen rates the evidence that SEMA4A causes each of these diseases.
Lynch syndrome (autosomal dominant): Disputed. An autosomal dominant hereditary neoplastic syndrome characterized by the development of colorectal carcinoma and a high risk of developing endometrial carcinoma, gastric carcinoma, ovarian carcinoma, renal pelvis carcinoma, and small intestinal carcinoma.
Homologues: Orthologues: chimpanzee SEMA4A (99% identical), macaque SEMA4A (97% identical), guinea pig SEMA4A (86% identical), pig SEMA4A (86% identical), rat Sema4a (84% identical), mouse Sema4a (84% identical), dog SEMA4A (84% identical), rabbit SEMA4A (84% identical), tropical clawed frog sema4a (44% identical). Paralogues in human: SEMA4B (38% identical), SEMA4D (34% identical), SEMA4C (33% identical), SEMA4G (32% identical), SEMA4F (29% identical), SEMA5B (28% identical), SEMA3A (27% identical), SEMA3D (27% identical), SEMA3F (27% identical), SEMA3B (26% identical), SEMA6D (26% identical), SEMA5A (26% identical), and 7 more.
Diseases named in the same sentence as SEMA4A in open-access papers:
SEMA4A is named in the same sentence as 83 diseases in open-access papers, as found by Europe PMC text mining. Sharing a sentence is not in itself a finding about the gene and the disease. The quoted sentences say what the papers report.
breast carcinoma (11 papers, 2014 to 2025). "Previous studies have demonstrated that SEMA4A plays a role in facilitating the proliferation and metastasis of breast carcinoma." (PMID 39062540, 2024). "Semaphorin class 4A (SEMA4A) is a transmembrane semaphorin that was reported to be overexpressed in the serum and tissue of breast cancer patients compared to their respective normal controls." (PMID 37685898, 2023). "SEMA4A, 4C and 4D were the three most famous family members found to be involved in the development of multiple malignancies such as breast cancer, colorectal cancer, cervical cancer and ovarian cancer." (PMID 35676688, 2022). "Recent studies have shown a dysregulation of Sema4A expression in several types of cancer such as hepatocellular carcinoma, colorectal, and breast cancers." (PMID 30598022, 2018). "A more recent study connected the increased Sema4A expression in breast cancer tissues with disease progression." (PMID 30598022, 2018). "Secondly, this study implies the protective role of NRP-1, SNAI1 and SEMA4A expression in PBMCs in healthy controls and early stage breast cancer patients." (PMID 28607365, 2017). "The molecular mechanism governing the ability of SNAI1 and SEMA4A in PBMCs to safeguard the initiation or progression of breast cancer needs to be studied in further detail to determine methods to tap this defensive mechanism in treating cancer patients." (PMID 28607365, 2017). "On the contrary, the decreased expression of NRP-1 in addition to SNAI1 and SEMA4A in PBMCs in the cancer cohort studied compared to healthy controls highlights their potential protective role against breast cancer." (PMID 28607365, 2017). "Of these, genes hypothesized to have a tumor-suppressor function included LINC00886, MAN2C1, SNUPN, and STC1, while YBEY, SEMA4A, and MUTYH may have an oncogenic role in breast carcinogenesis based on their associations with breast cancer risk." (PMID 32139696, 2020). "Thus, the decreased expression of SEMA4A in PBMCs in our breast cancer cohort implies a malfunction in the adaptive immune response against tumor cells." (PMID 28607365, 2017). "The expression of SEMA4A in hypoxic TNBC cells was associated with apoptotic resistance and increased cell proliferation —all of which suggest that the expression of SEMA4A is protective to hypoxic breast cancer cells and confers a greater survival advantage against the toxic effects of hypoxia." (PMID 37685898, 2023). "As Sema4A has been reported to be involved in the progression of breast cancer and its expression was higher in the tissues and serum of patients when compared with normal tissues, these results could promote the use of Sema4A as a potential target for treatment of breast carcinoma." (PMID 33858502, 2021). "The newly identified role of PLXNB2 in CTC clustering in conjunction with its ligands SEMA4C in tumor cells and SEMA4A in monocytes promotes metastasis, and is correlated with lower OS and DMFS in the context of advanced breast cancer, TNBC in particular." (PMID 40818975, 2025). "Conversely, in PBMCs, NRP-1 and its interacting molecules SEMA4A and SNAI1 are significantly downregulated in breast cancer patients compared to healthy controls, indicating a protective role." (PMID 28607365, 2017). "Breast cancer patients displayed significantly decreased expression of NRP-1 (p < 0.0001), SNAI1 (p < 0.0001) and SEMA4A (p < 0.0001) in PBMCS compared to healthy controls." (PMID 28607365, 2017). "Only SEMA4A V78M segregated with all CRC cases and was also detected in individuals K9 with testicular and K14 with breast cancer, respectively." (PMID 25307848, 2014). "Chromatin immunoprecipitation assay evidenced the ability of HIF-1α, but not HIF-2α, to bind the promoter of Sema4A gene, in cooperation with hypoxia in breast cancer cells." (PMID 33858502, 2021).
multiple sclerosis (8 papers, 2015 to 2025). A progressive autoimmune disorder affecting the central nervous system resulting in demyelination. "Reflecting the function as T cell activator, the development of myelin oligodendrocyte glycoprotein (MOG)-induced experimental autoimmune encephalomyelitis (EAE), an animal model of multiple sclerosis (MS), is improved in Sema4A-deficient mice partly due to impaired Th1 and Th17 differentiation." (PMID 32169103, 2020). "Recent attention has focused on the regulatory role of SEMA4A in immune cells, particularly in conditions like multiple sclerosis." (PMID 40756031, 2025). "Accordingly, in multiple sclerosis, high serum Sema4A levels correlate with the elevated serum IL-17A, earlier disease onset, and increased disease severity." (PMID 39737847, 2024). "We previously demonstrated that patients with multiple sclerosis (MS) of high serum Sema4A levels are resistant to IFN-β therapy." (PMID 29518148, 2018). "The chief cellular source of Sema4A within the multiple sclerosis plaques appears to be infiltrating lymphocytes and microglia." (PMID 26024919, 2015). "Blocking antibodies to Sema4A result in decreased clinical and histopathological severity in the mouse model of multiple sclerosis (MS), experimental autoimmune encephalomyelitis, which is a prototypical Th1-mediated autoimmune disorder." (PMID 26024919, 2015). "We found that Sema4A protein levels are increased within multiple sclerosis plaques compared with normal-appearing white matter and that Sema4A induces lactate dehydrogenase release in a human OL cell line." (PMID 26024919, 2015). "In addition, dendritic cell-originated Sema4A might play a role in the activation of both Th1 and Th17 cells in the neuroinflammatory demyelinating autoimmune disease, multiple sclerosis." (PMID 35054504, 2022). "This receptor is also involved in the Sema4B-mediated inflammation in microglia/macrophages, the Sema4D-mediated cartilage destruction, the Sema4A-induced secretion of IL-17 by CD4+ T cells of systemic sclerosis patients and the Sema4D-mediated inflammation in a mouse model of multiple sclerosis." (PMID 40598553, 2025). "Sema4A is a regulator of helper T cell (Th) activation and differentiation in the priming phase, which plays an important role in the pathogenesis of experimental autoimmune encephalomyelitis (EAE) and multiple sclerosis (MS)." (PMID 32169103, 2020). "It has also been shown that SEMA4A-Plexin-D1 contributed to the elevated IL-4 and IL-17 in patients with systemic sclerosis (SSc), and the same manner can be seen for other T CD4+ mediate diseases, including asthma, rheumatoid arthritis (RA), and multiple sclerosis (MS)." (PMID 38148815, 2024).
asthma (7 papers, 2018 to 2024). "In contrast, in neonatal mice, pDC-derived semaphorin 4a induced the expansion of Treg cells, which controlled susceptibility to viral bronchiolitis and subsequent viral challenge–induced asthma in later life." (PMID 32020335, 2020). "This research is a first step in generating potent mutant Sema4A molecules with stimulatory function for Treg cells with a view to designing immunotherapeutics for asthma." (PMID 35328445, 2022). "It is important, however, to verify that such Sema4A mutants lack binding to potentially asthma-upregulating Sema4A receptors such as ILT4 and Plexin D1." (PMID 35328445, 2022). "Several studies have shown that Sema4A expression is elevated in diseases in which Th cells play an essential role, including asthma, RA, MS and SSc." (PMID 32971928, 2020). "To assess the role of Sema4A in allergen-induced lung inflammation, we used OVA model of asthma in Sema4A−/− mice where we found an exaggerated lung allergic response as compared to WT mice." (PMID 30598022, 2018). "We plan to expand this study to include other functionally critical residues in Sema4A, their combinations, and explore the functional activity of novel mutant Sema4A proteins to treat asthma and, potentially, other chronic inflammatory conditions where Treg cells play essential regulatory roles." (PMID 35328445, 2022). "These residues are localized to the Sema4A-Plexin B1 interface and may participate in the Sema4A functions in an experimental model of asthma and in human Treg cell stability." (PMID 35328445, 2022). "Additionally, Sema4A treatment alters DC maturation, reduces their ability to activate T-cells, and decreases the polarization of Th2 cells, thereby reducing allergic inflammation in asthma." (PMID 39213301, 2024). "Therefore, certain functional parallels can be drawn between these two distinct semaphorins, Sema3E and Sema4A, but to this day it is unclear if their seeming functional likeness in some diseases—asthma, for example—is directly related to their signaling through Plexin D1." (PMID 30598022, 2018). "pDC depletion or Sema4a blockade in neonates abrogated Treg expansion during PVM infection, as well severe bronchiolitis and asthma in later life, suggesting that pDCs limit PVM-induced immunopathology by expanding Tregs." (PMID 31952261, 2020).
rheumatoid arthritis (7 papers, 2015 to 2024). A chronic, systemic autoimmune disorder characterized by inflammation in the synovial membranes and articular surfaces. "This study suggests that Sema4A might serve as a diagnostic and prognostic marker for the initiation, progression, and therapeutic intervention of rheumatoid arthritis." (PMID 30134791, 2018). "Wang and associates assessed the significance of Sema4A-Plexin B1 pathway in the inflammatory response in rheumatoid arthritis (RA) by using human synovial fibroblasts of RA (RASFs) in in vitro cultures." (PMID 38259471, 2023). "A study has reported that Sema4A can aggravate the pathological progression of rheumatoid arthritis by synergistically regulating the generation of IL-6 with lipopolysaccharide." (PMID 37901456, 2023). "However, to date, the exact expression amounts and function of Sema4A in RA, especially synovial fibroblasts of rheumatoid arthritis (RASFs), remain to be determined." (PMID 26303122, 2015). "Thus, distinct effects of Sema4A on different cell types, even if using the same receptor, should be taken into account when designing a therapeutic strategy to either potentiate (for allergic asthma) or inhibit (for rheumatoid arthritis) its activity." (PMID 30134791, 2018).
allergic disease (4 papers, 2018 to 2024). An immune response that occurs following re-exposure to an innocuous antigen, and that requires the presence of existing antibodies against that antigen. "Semaphorin 4A (Sema4A), one of the immune semaphorins, plays both pathogenic and therapeutic roles in autoimmune diseases, allergic diseases, and cancer." (PMID 39737847, 2024). "To further define the potential roles of SEMA4A in the pathophysiology of human allergic disease, we examined mRNA and protein expression of Sema4A in lung tissues obtained from patients with allergic asthma and normal lung tissues." (PMID 29467366, 2018). "Sema4A, another member of the Semaphorins family, could promote the activation of eosinophils and mediate occurrence of allergic diseases." (PMID 38111650, 2023). "Therefore, Sema4A serves as a downregulatory molecule for allergic diseases suppressing allergen-dependent and -independent responses, in part, by upregulating Treg cell response." (PMID 30598022, 2018). "On the other hand, the Sema4A pathways are dysregulated in different diseases such as retinal degenerative diseases (retinitis pigmentosa type 35 and cone-rod dystrophy type 10), allergy, infectious and autoimmune diseases, and certain types of cancer." (PMID 30598022, 2018).
experimental autoimmune encephalomyelitis (4 papers, 2015 to 2024). An autoimmune demyelinating disease of the central nervous system that is produced experimentally in animals by the injection of homogenized brain or spinal cord in Freund's adjuvant. "The implications of Sema4A on the efficacy of fingolimod were investigated by administering recombinant Sema4A-Fc and fingolimod to mice with experimental autoimmune encephalomyelitis (EAE)." (PMID 29518148, 2018). "Sema4A reportedly binds to the Tim2 receptor in the immune system, and antibodies to Sema4A reduce the severity of neurological symptoms in the experimental autoimmune encephalomyelitis demyelinating animal model." (PMID 26024919, 2015). "Consistent with these clinical observations, we showed IFN-β non-responsiveness in experimental autoimmune encephalomyelitis (EAE) mice with high serum Sema4A state." (PMID 29518148, 2018).
lung carcinoma (4 papers, 2018 to 2025). "In particular, increase of NF-kB activated an increase of Sema4A which in turn up-regulated NF-kB, facilitating the development of lung cancer and osteoarthritis." (PMID 40276507, 2025). "As a translational part of our research, we obtained human lung cancer tissue arrays (Z7020065, BioChain) and assessed them for Sema4A and corresponding receptor expression using commercially available antibodies." (PMID 30598022, 2018). "We analyzed the expression of Sema4A and Plexin D1 on human lung cancer tissue arrays using immunohistochemistry with corresponding Abs." (PMID 30598022, 2018). "Although SEMA4A is not proved to be associated with Lung Cancer yet, it is related to Lung Inflammation and Colorectal Cancer, and its role in Lung Cancer genesis might be discovered in the future." (PMID 31001321, 2019).
Autoimmunity (3 papers, 2015 to 2020). The occurrence of an immune reaction against the organism's own cells or tissues. "Our observations suggest that Sema4A on monocytes play an essential role in augmenting the tissue inflammation in CNS autoimmunity." (PMID 32169103, 2020). "Semaphorin 4A (Sema4A) plays critical roles in many physiological and pathological processes including neuronal development, angiogenesis, immune response regulation, autoimmunity, and infectious diseases." (PMID 26303122, 2015). "Recently, a Sema4A-neuropilin-1 (Sema4A-NRP1) axis was reported to maintain T regulatory (Treg) cell stability, highlighting this pathway as a potential therapeutic target that could limit Treg-cell-mediated tumor-induced tolerance without inducing autoimmunity." (PMID 26303122, 2015).
colorectal cancer (3 papers, 2014 to 2022). A primary or metastatic malignant neoplasm that affects the colon or rectum. "Compared with wild-type protein, SEMA4AV78M demonstrates significantly increased MAPK/Erk and PI3K/Akt signalling as well as cell cycle progression of SEMA4A-deficient HCT-116 colorectal cancer cells." (PMID 25307848, 2014). "It is known that hereditary factors contribute to familial colorectal cancer type X. Here, the authors uncover the SEMA4A p.Val78Met germline mutation and show that the protein product is associated with changes in cell cycle progression in colorectal cancer cells." (PMID 25307848, 2014).
hepatocellular carcinoma (3 papers, 2018 to 2023). A malignant tumor that arises from hepatocytes. "More importantly, a published experiment has suggested that knockdown of Sema4A can improve the EMT process and increase sensitivity to doxorubicin (a chemotherapy agent for treating hepatoma) in hepatoma cells (Pan, Wang & Ye, 2016)." (PMID 37901456, 2023).
melanoma (3 papers, 2021 to 2022). A malignant, usually aggressive tumor composed of atypical, neoplastic melanocytes. "Indeed, specific deletion of Nrp-1 in Treg cells (Nrp1f/fFoxp3Cre mice) or blockade of Nrp-1 with Sema4a mAb, Nrp-1 mAb and Sema4a-Ig significantly decreased tumor growth in the B16F10 melanoma mouse model." (PMID 34539668, 2021). "Sema4A expression enhances B-cell infiltration, which contributes to favorable outcome for head and neck squamous cell carcinoma, and Sema4A expression on DCs activates CTL and exerts anti-tumor in Lewis lung cancer, whereas Sema4A maintains the stability and function of Tregs in melanoma." (PMID 35155237, 2022). "At protein level, several semaphorins, plexins and neuropilins have been detected in tissue cancer available in the database, including melanoma, except for Sema4A, Sema4F, Sema4G, Sema6B, plexinA4, plexinB3 for which melanoma specimens resulted weakly positive or prevalently negative." (PMID 33858502, 2021).